NCAPG2 (non-SMC condensin II complex subunit G2)
Diseases named in the same sentence as NCAPG2 in open-access papers (continued):
Sharing a sentence is not in itself a finding about the gene and the disease.
sarcoma (1 paper, 2023). A usually aggressive malignant neoplasm of the soft tissue or bone. "By evaluating NCAPs in normal and sarcoma tissues using the GEPIA database, we noticed significantly higher expression patterns of NCAPD2, NCAPG, NCAPH, NCAPG2, and in sarcoma samples compared to normal tissues." (PMID 37192046, 2023). "GEPIA database showed that high expression of NCAPD2, NCAPH, NCAPG and NCAPG2 had a significant correlation with poor overall survival of sarcoma patients (P < 0.05)." (PMID 37192046, 2023). "In GEPIA dataset, we verified that the overexpression of NCAPG2 was positively correlated with low DFS of sarcoma patients." (PMID 37192046, 2023). "Six members of the NCAPs family, including NCAPD2, NCAPG, NCAPH, NCAPD3, NCAPG2, and NCAPH2, have been found in different types of sarcomas." (PMID 37192046, 2023). "In this study, ONCOMINE, GEPIA, Kaplan-Meier plotter, DAVID (KEGG and GO analysis), and TIMER datasets were utilized to study the high expression, prognosis analysis, signal pathway and immune correlation of NCAPD2, NCAPG, NCAPH, NCAPD3, NCAPG2, and NCAPH2 in sarcoma for the first time." (PMID 37192046, 2023). "In addition, the high expression of NCAPG2 was also correlated with the poor overall survival and disease-free survival of sarcoma patients, but with no significance (p > 0.05)." (PMID 37192046, 2023). "Up to now, NCAPD2, NCAPG, NCAPH, NCAPD3, NCAPG2, and NCAPH2 have not been mentioned in sarcoma, except NCAPG mentioned in Ewing sarcoma." (PMID 37192046, 2023).
squamous carcinoma (1 paper, 2017). "We performed qRT‐PCR and Western blot analysis to determine the expression level of NCAPG2 in six human NSCLC cell lines which include both squamous carcinoma and AD." (PMID 27862966, 2017).
cancer (29 papers, 2013 to 2026). A tumor composed of atypical neoplastic, often pleomorphic cells that invade other tissues. "NCAPG2 maintained be closely associated with various inflammatory cells in most cancers, including macrophages, M2 macrophages, T cells, Tregs, CAFs, monocytes, neutrophils, and NK cells." (PMID 37501987, 2023). "To further elucidate the association between NCAPG2 and infiltrated inflammatory cells in these cancers, we applied six of the latest algorithms (TIMER, EPIC, quanTIseq, MCP-counter, CIBERSORT, and xCell) to quantify immune cells." (PMID 37501987, 2023). "DFI analysis indicated that NCAPG2 serves as a risk agent for 5 cancer types (CESC, KIPAN, KIRP, LIHC, and PAAD) and as a protective factor in STAD and UCS." (PMID 37501987, 2023). "Overall, these findings suggest that NCAPG2 is associated with an immunosuppressive microenvironment in cancers." (PMID 37501987, 2023). "Using the cBioportal dataset, we analyzed frequency changes and mutations in NCAPG2 across multiple cancers." (PMID 37501987, 2023). "These associations underscore the significance of NCAPG2 in the pathophysiology of cancer, highlighting its potential for targeted therapy and biomarkers in disease progression, thereby emphasizing the innovative nature of our investigation into its functional roles and clinical implications." (PMID 40447854, 2025). "NCAPG2 has been reported to be associated with tumorigenesis in various types of cancer." (PMID 37501987, 2023). "Furthermore, we systematically collected and integrated protein data, as well as clinical features, using the UALCAN database and found that NCAPG2 was associated with clinical stage and prognosis in various cancers." (PMID 37501987, 2023). "Although the function of NCAPG2 during mitosis has been well defined, the expression status, functional role and underlying mechanism of NCAPG2 during oncogenesis and cancer proliferation remain unclear." (PMID 27862966, 2017). "According to this research, we assessed the expression levels of NCAPG2 across different types of cancer and then confirmed its elevated expression specifically in CHOL." (PMID 40447854, 2025). "In the context of cancer, it is well documented that NCAPG2 is often highly expressed and significantly contributes to tumor proliferation, metastasis and invasion." (PMID 40552444, 2025). "Similar cytoplasmic functions were found for CHROMR in certain cancers where it targets miR-27b-3p, miR-186-5p, and miR-1299, repressing cell cycle-regulator genes CNNM1, MET, and NCAPG2, leading to accelerated cancer growth and progression." (PMID 40559622, 2025). "NCAPG2 promotes PCa malignancy and drives cancer stemness via the STAT3/c-MYC signaling axis, highlighting its potential as a therapeutic target for PCa." (PMID 38166947, 2024). "Given the regulatory relationship between NCAPG2 and c-MYC, and aberrant c-MYC overexpression has been linked to cancer cell stemness, we further explored the potential role of NCAPG2 in PCa-CSCs." (PMID 38166947, 2024). "NEIL3 initiates base excision repair to maintain genomic stability, and NCAPG2 is involved in mitosis, DNA repair, and histone regulation and has a vital role in inhibiting cancer cell proliferation." (PMID 37509173, 2023). "Upon further assessment of NCAPG2 expression levels at different clinical and pathological stages from a pan-cancer angle, significant difference was observed in 11 tumors." (PMID 36776838, 2023). "The levels of NCAPG2 were found to be positively correlated with TMB in several types of cancer, including ACC, LUAD, PRAD, STAD, STES, and KICH." (PMID 37501987, 2023). "Studies on colon cancer have demonstrated that NCAPG2 holds promise as both a therapeutic target and a biomarker for cancer prognosis and treatment." (PMID 37501987, 2023). "The present study found that NCAPG2 displayed a significant correlation with ICI-related genes in most cancers, with a predominantly positive correlation." (PMID 36776838, 2023).
cancer (continued). "Overall, our analysis of multiple cancer samples revealed a positive correlation between NCAPG2 and infiltrated inflammatory cells." (PMID 37501987, 2023). "Further comparison of the results revealed that HMGB1 and NCAPG2 were all significantly positively related in pan-cancer, highlighting the necessity to further investigate the mechanisms involved." (PMID 36776838, 2023). "Next, for the purpose of exploring the significance of NCAPG2 on the tumor microenvironment (TME) by investigating the relationship between NCAPG2 and the level of immune infiltration in pan-cancer." (PMID 36776838, 2023). "Yet, although NCAPG2 has been previously documented in the before mentioned cancer types, studies in the context of the entire cancer spectrum, namely the pan-cancer, are currently absent." (PMID 36776838, 2023). "We analyzed data from the TCGA database to investigate the correlation between NCAPG2 expression and cancer prognosis." (PMID 37501987, 2023). "We also evaluated the immunotherapy value of NCAPG2 for various cancers using immunotherapy cohorts." (PMID 37501987, 2023). "The results are illustrated in, where NCAPG2 demonstrated remarkable correlations with the currently listed immunosuppressive/immunostimulatory genes in pan-cancer, with the majority of positively correlated immune checkpoint pathway genes." (PMID 36776838, 2023). "Subsequently, the ROC curves for each cancer type were plotted under the pan-cancer level, and the results showed that NCAPG2 had high accuracy (AUC>0.8) for the diagnosis of 18 cancers." (PMID 36776838, 2023). "We compared the potential correlation of NCAPG2 expression with 60 immune checkpoint pathway genes in pan-cancer." (PMID 36776838, 2023). "NCAPG2, a chromatin remodeling protein, has been reported to be highly expressed in numerous cancers." (PMID 37248471, 2023). "Accordingly, in the present study, we leveraged resources from databases such as TCGA and GTEx to conduct a pan-cancer analysis for NCAPG2 and to investigate its implications in cancer prognosis." (PMID 36776838, 2023). "We confirmed this possibility based on a pan-cancer expression analysis of the TCGA and GTEx databases, with NCAPG2 being statistically significantly and aberrantly highly expressed in almost all cancers except KIRP, KICH, THCA." (PMID 36776838, 2023). "We found that cancers showing the strongest relationship between NCAPG2 levels and each score were WT, GBM, and LUSC for immune scores; WT, GBM, and TGCT for estimate scores; and NB, GBM, and STAD for stromal scores." (PMID 37501987, 2023). "In this study, we aimed to systematically investigate the expression profile of NCAPG2 in multiple cancer types, using transcriptional and clinical data from public datasets." (PMID 37501987, 2023). "Nevertheless, evaluation of NCAPG2 in previous studies remains limited to a few cancers; therefore, the clinical implications and biological functions of NCAPG2 in cancer as a whole are still unclear and require further clarification." (PMID 37501987, 2023). "NCAPG2 was elevated in diverse human cancer tissues and correlated with clinicopathological features and poor prognosis." (PMID 35664767, 2022). "We also examined NCAPG2 expression in paired cancer tissues and adjacent normal tissues in human cancer using the TCGA datasets." (PMID 35664767, 2022). "In this study, we determined that NCAPG2 was up-regulated in various human cancers and especially in LGG." (PMID 35898895, 2022). "We explored the mRNA expression levels of NCAPG2 in tumor tissues and adjacent tissues from 33 types of cancer via the TCGA dataset and GTEX databases." (PMID 35664767, 2022). "Taking our expression analysis and validation analyses together, NCAPG2 was upregulated in various human cancers." (PMID 35664767, 2022). "We found that NCAPG2 expression was significantly higher in 16 of the 18 cancers compared with normal tissue." (PMID 35664767, 2022).
cancer (continued). "We used the TCGA and GTEx databases to examine the expression of NCAPG2 in various cancers, the results showed that NCAPG2 increased in LGG, GBM tissue compared to the normal tissues based on TCGA and GTEx datasets." (PMID 35898895, 2022). "We also examined NCAPG2 expression in paired cancer tissues and adjacent normal tissues in human cancer using TCGA datasets." (PMID 35898895, 2022). "Our research presented that the mRNA expression levels of NCAPG2 were increased in 28 of the 33 cancers compared with normal tissue." (PMID 35664767, 2022). "Our studies demonstrated for the first time the expression profile and functional role of NCAPG2 in human cancer." (PMID 27862966, 2017). "Previous research has established a relationship between NCAPG2 expression levels and tumorigenesis, particularly in cancers such as breast and colorectal cancer, where its overexpression has been associated with poor prognosis and aggressive disease phenotypes." (PMID 40447854, 2025). "Therefore, we assessed the correlation between NCAPG2 methylation and the expression of immunoinhibitors and immunostimulators across different human cancers." (PMID 40447854, 2025). "Finally, we identified that NCAPG2 was positively correlated with cancer stem cell (CSC) markers and enhanced self-renewal capacity of PCa cells." (PMID 38166947, 2024). "NCAPG2 has attracted considerable attention in several cancers as a key player in cell mitosis." (PMID 38637125, 2024). "Finally, given the link between c-MYC and cancer stemness, we identified that NCAPG2 was positively correlated with PCa CSC properties." (PMID 38166947, 2024). "Overall, however, the correlation was mostly negative, for example in GBM, where it was the highest correlation among the pan-cancers, which may explain, to some extent, the crucial role of NCAPG2 in GBM." (PMID 36776838, 2023). "However, we discovered that NCAPG2 was negatively correlated with MSI in other cancers, such as DLBC, GBMLGG, HNSC, and THCA." (PMID 37501987, 2023). "Finally, we utilized public databases to predict the immunotherapy response and identify candidate small-molecule drugs that exhibit sensitivity across multiple cancer types, based on the expression of NCAPG2." (PMID 37501987, 2023). "Whether TMB or MSI, the expression of NCAPG2 in a pan-cancer was mostly positively correlated with its expression level." (PMID 36776838, 2023). "In pan-cancer, NCAPG2 correlated strongly with these three scores." (PMID 36776838, 2023). "By combining and digging into the resources of TCGA, GTEx databases, we obtained the expression levels of NCAPG2 under a pan-cancer perspective, indicating that NCAPG2 was statistically over-expressed in 22 common malignancies, including GBM, CESC, LUAD and others." (PMID 36776838, 2023). "Simultaneously, the genetic properties of NCAPG2 hint that it might have enormous potential to interpret the malignant progression of tumors in a broader perspective, that is, in pan-cancer." (PMID 36776838, 2023). "The results demonstrated that NCAPG2 expression significantly contributed to the level of immune cell infiltration in the majority of cancer types, with macrophages, natural killer cells and neutrophils being the three immune cell types most closely related to NCAPG2 expression." (PMID 36776838, 2023). "Overall, future research on NCAPG2 expression and its impact on TMEs could potentially lead to the development of more effective and personalized immunotherapy-based anti-cancer strategies." (PMID 37501987, 2023). "Our study revealed that NCAPG2 could be utilized as an immune-related biomarker for both diagnosing and predicting the prognosis of multiple cancer types." (PMID 37501987, 2023). "Finally, a recent HotNet2 Pan-Cancer analysis suggested that multiple cancers harbor rare mutations in SMC2, SMC4, NCAPD2, NCAPD3, NCAPH2 and NCAPG2, supporting a tumor-suppressor role for condensin proteins." (PMID 36169232, 2022).
cancer (continued). "However, the potential molecular mechanisms of NCAPG2 in cancer progression need to be explored in further studies." (PMID 35664767, 2022). "Finally, in vitro experiments demonstrated that NCAPG2 maintains cancer stemness and promotes erlotinib resistance in LUAD cells." (PMID 36139554, 2022). "Mounting evidence has shown that NCAPG2 is differentially expressed in various cancers." (PMID 35898895, 2022). "However, abnormal overexpression of KIF15 and NCAPG2 has been detected in many other types of cancer." (PMID 32582275, 2020). "Moreover, inhibition of NCAPG2 suppressed cancer cell proliferation via leading to G2/M phase arrest through alterations of p27, p21, Cyclin B1 and Cdc2 expression." (PMID 27862966, 2017). "Based on the cancer‐specific expression and the functional characteristics, our results indicated that NCAPG2 could serve as a potential prognosis marker and a novel therapeutic target for NSCLC patients." (PMID 27862966, 2017). "It is well known that NCAPG2 plays a critical role in cell mitosis; however, the role of altered NCAPG2 expression and its transcriptional regulatory function in cancer development remains mostly unknown." (PMID 27862966, 2017). "Notably, NCAPG2 was consistently found to be upregulated in multiple cancers, including LIHC." (PMID 40552444, 2025). "NCAPG2 is expressed in different cell types, and the abnormal increase could affect the cell's chromosome assembly and segregation process, thus playing a role in cancer cell proliferation and metastasis." (PMID 38637125, 2024). "Moreover, NCAPG2 could promote PCa malignancy and drive cancer stemness through a previously unreported STAT3/c-MYC signaling-dependent mechanism, which provides a new direction for targeted PCa therapy." (PMID 38166947, 2024). "NCAPG2, a subunit of the chromosomal condensin II complex, is increasingly recognized for its role in tumor evolution and might act as a pan-oncogene with a unique role in the evolution of various cancers." (PMID 36776838, 2023). "Additionally, we assessed the relationship between the stemness index and NCAPG2 and found that it was significantly correlated with NCAPG2 in pan-cancer, which exhibited parallels with prognostic outcomes, suggesting that NCAPG2 influences stemness progression." (PMID 36776838, 2023). "It has previously been reported that NCAPG2 could be participated in multiple malignant tumors." (PMID 33344773, 2020). "However, the expression profile and functional role of NCAPG2 in human cancer remains largely unknown." (PMID 27862966, 2017). "In cancer, CHROMR binds additional miRNAs (e.g., miR-27b-3p, miR-186-5p, miR-1299) that repress cell cycle regulators such as CNNM1, MET, and NCAPG2, thereby promoting tumor proliferation and metastasis." (PMID 40559622, 2025). "We verified the four up-regulated lncRNAs (TCONS_00020615, TCONS_00055555, TCONS_00106091, and TCONS_00130858) and eight cancer-related mRNAs (CDCA3, DIAPH3, MCM7, NCAPG2, TPD52, PRC1, SETD6, and KIF22) involved in the ceRNA network by qRT-PCR." (PMID 37098483, 2023). "Survival analysis of NCAPG2 in four domains including OS, DSS, PFS and DFS reveals its prognostic value in pan-cancer." (PMID 36776838, 2023). "The condensin complex has been suggested as a potential therapeutic target for cancer, and human homologs YCG1/NCAPG2, YCS4/NCAPD2, and SMC4/SMC4 are synthetic lethal with the Ras oncogene." (PMID 31660150, 2019). "Using publicly available patient derived datasets obtained from TCGA, we determined that all eight condensin genes (SMC2, SMC4, NCAPD2, NCAPD3, NCAPG, NCAPG2, NCAPH, and NCAPH2) are frequently altered in at least 12 common cancer types." (PMID 31357676, 2019). "Unlike HMGB1, IFNA1, IFNA2, IL-2, KIR2DL3, IL-13 and NCAPG2 demonstrated an intuitive correlation in only a few cancer types." (PMID 36776838, 2023).
cancer (continued). "As TMB and MSI seem to be the key factors in determining whether to undertake an immune checkpoint therapy or not, we have investigated and compared the correlation between NCAPG2 expression and TMB as well as MSI in a pan-cancer." (PMID 36776838, 2023). "According to the Genomics of Drug Sensitivity in Cancer (GDSC) database, there is a negative association between NCAPG2 levels and drug sensitivity." (PMID 37501987, 2023). "NCAPG2 (non-SMC condensin II complex subunit G2) has been shown to be upregulated in various human cancers." (PMID 35664767, 2022). "The six hub genes (BIRC5, TOP2A, FANCI, NCAPG2, RAD51, and RRM2) were reported to be critical to regulate cell cycle, and their abnormal expression could lead to development and progression of cancers." (PMID 32902196, 2020). "However, data on the pathological mechanisms of NCAPG2 in pan-cancers remain lacking." (PMID 37501987, 2023). "According to the Cancer Therapeutics Response Portal (CTRP) dataset, there is a negative correlation between NCAPG2 and drug sensitivity." (PMID 37501987, 2023). "Notably, although NCAPG2 significantly contributed to the infiltration of immune cells overall, this relationship was not prominent in CHOL, COAD and other cancer types." (PMID 36776838, 2023).